LDHA (lactate dehydrogenase A)
Diseases named in the same sentence as LDHA in open-access papers (continued):
Sharing a sentence is not in itself a finding about the gene and the disease.
tumor (continued). "In another approach, small interference RNA (siRNA) cationic lipid-assisted NPs (CLAN) were designed to neutralize tumor acidity by inactivating lactate dehydrogenase A (LDHA)." (PMID 35335881, 2022). "The evidence highlighted that METTL3 enhanced LDHA expression, catalyzing the conversion of pyruvate to lactate, thereby promoting glycolysis and enhancing chemotherapy tolerance to 5-FU in tumor cells." (PMID 36778600, 2022). "Transcription of gene-encoding glycolytic enzymes is activated by HIF-1α, including stimulation of glycolysis by upregulation of LDHA, which creates an acidic tumor microenvironment." (PMID 35342404, 2022). "In neoplastic diseases, the high activity of LDHA produces large amounts of lactate, which is secreted by cancer cells." (PMID 36077374, 2022). "FGF/FGFR1 signaling induces glycolysis and FGFR1 phosphorylates LDHA, where FGFR1 expression induces p-LDHA level and activates LDHA activity in tumor cells." (PMID 36077431, 2022). "Spheroids from single and double LDHA/B KO cells were injected into immunodeficient mice to evaluate in vivo tumor development and survival." (PMID 36278433, 2022). "In conclusion, GP5, CCT7, UQCRC1, PGD, GAPDH and LDHA have been found to play a role in tumor development, prognosis and even diagnosis in previous studies." (PMID 36404333, 2022). "LDHA was significantly upregulated in PCa tumor specimens compared with normal prostate tissues by bioinformatics analysis from TCGA cancer database and qRT-PCR." (PMID 35571619, 2022). "Tumour epithelial LDHA expression correlated positively with lactate SNR, pyruvate SNR, and kPL, with the latter two correlations reaching statistical significance (rs = 0.64 and 0.66, P = 0.04 and 0.03, respectively)." (PMID 35075123, 2022). "Our data clarified that inhibition of LDHA attenuates glycolysis and suppresses tumor proliferation in ABC-DLBCL." (PMID 35359405, 2022). "Tumor cells generally stain intensely for LDHA, although unevenly within the same cluster of tumor cells." (PMID 36555705, 2022). "Currently, gossypol (AT-101) and its derivatives FX-11, galloflavin, and N-hydroxy indole-based compounds have been shown to selectively and preferentially inhibit LDHA and suppress tumor progression." (PMID 36588722, 2022). "It has been reported that LDHA was pivotal for cell viability and tumor cell proliferation and elevated expression of serum LDH is associated with poor prognosis in DLBCL patients." (PMID 35359405, 2022). "Although the regulatory mechanisms of LDHA have been explored in some studies, he therapeutic significance of tumour lactate metabolism has yet to be established." (PMID 36578477, 2022). "To validate the observed increase in LDHA expression in GP5 tumours, we analysed the nuclear expression of HIF-1α using IHC." (PMID 35075123, 2022). "Specifically, lactate dehydrogenase A (LDHA) is responsible for converting pyruvate to lactate which has been shown to promote tumor progression by regulating angiogenesis, metastasis, therapeutic resistance as well as chronic inflammation and immune escape." (PMID 36418319, 2022). "High-level LDHA promotes tumor cell formation and progression by facilitating epithelial to mesenchymal transformation, angiogenesis, cytoskeletal remodeling, cell invasion, and migration." (PMID 35646923, 2022). "Many of these studies relied on tumor-derived lactic acid or knockout models of lactate dehydrogenase A or monocarboxylate transporter, which include the convoluted effects from lactate, tumor acidity and altered cancer cell metabolism." (PMID 36068198, 2022). "The impact of LDHA inhibition on tumor growth in vivo seems to extend beyond a cell-autonomous effect and to involve the enhancement of immunosurveillance mechanisms." (PMID 35205318, 2022). "In conclusion, our results indicate that LINC01128 promotes tumor growth and regulates LDHA protein expression in vivo." (PMID 35193567, 2022).
tumor (continued). "LDHA was also an essential enzyme in lactate production, which was reported to create an acidic tumor microenvironment and mediate immunotolerance." (PMID 36138435, 2022). "We found that tumors with the highest levels of tumor-cell LDHA expression displayed a significantly reduced infiltration of stromal TILs (left), and of CD3+ (middle) and CD8+ (right) lymphocytes (p = 0.001, 0.003 and 0.015, respectively)." (PMID 36505421, 2022). "In line with this, lower lactate production in melanoma tumors with downregulated LDHA expression increased infiltration of T and NK cells, which slowed down tumor growth." (PMID 36582801, 2022). "As discussed in Section 2, LDHA inhibition prevents the conversion of pyruvate into lactate, inhibiting the process of aerobic glycolysis, which can be critical for tumor growth." (PMID 35205318, 2022). "Among the six metabolic genes, LDHA catalyzes the conversion of pyruvate and participates in the TCA cycle and has been reported to associate with tumor growth, maintenance, and invasion of HCC." (PMID 36250026, 2022). "Growing evidence is also showing a relationship between the upregulation of lactate dehydrogenase A (LDHA) and the proliferation of tumor cells." (PMID 35250999, 2022). "Upregulation of GLUT1, HK1, pyruvate kinase-M2 splice isoform, and LDHA enhances the Warburg effect in tumor cells." (PMID 35310040, 2022). "Of note, we also found that NOX4 expression positively correlated with HIF1α (resistant marker), Glut1 and LDHA (glycolytic markers), and Ki67; whereas it negatively correlated with Bcl2 in tumor tissues in patients with PTC." (PMID 35396551, 2022). "The suppression of KLF4 significantly increased LDHA expression and was correlated with the development and progression of cancer, whereas overexpression of KLF4 inhibited LDHA expression, aerobic glycolysis, and tumor size in in vivo and in vitro models." (PMID 36551514, 2022). "Due to LDHA upregulation, tumor cells acquire an aggressive phenotype characterized by cytoskeletal remodeling, angiogenesis, or increased invasiveness and migration." (PMID 36551514, 2022). "Glycolysis-reprogramming blockers for tumor metabolic pathways have been developed at the GPI or LDHA/B inhibitors." (PMID 36077431, 2022). "Numerous studies have confirmed the elevated LDHA levels in several different cancer types and highly expressed LDHA-mediated tumor immune escape by inhibiting immune killing and promoting immunosuppression." (PMID 36518315, 2022). "In vivo and in vitro experiments revealed that miR-223 promoted tumor growth and that the effects of miR-223 on tumor growth were primarily related to the inhibition of Fbw7-mediated LDHA’s ubiquitination." (PMID 35359405, 2022). "In the current study, we demonstrated that an EBV‐encoded miRNA, EBV‐miR‐BART18‐3p, significantly promotes tumor growth and facilitates de novo lipogenesis in CRC by regulating the SIRT1/HIF1α/LDHA/FASN axis." (PMID 36307872, 2022). "In xenografted mice, silencing RPN2 expression reduced tumor growth, ROS production, and levels of Ki-67, Vimentin, LDHA, and p-Akt/Akt, but enhanced E-cadherin expression." (PMID 35156537, 2022). "Increased levels of LDHA are frequently observed in human malignancies, and silencing LDHA expression or using specific inhibitors against LDHA activity in some tumor cells was found to reduce lactate secretion, cell viability, and their ability to invade." (PMID 36555705, 2022). "There is also growing evidence linking the overexpression of lactate dehydrogenase A (LDHA) to the growth of tumor cells." (PMID 36430837, 2022). "Only for advance NSCLC, high vs. low tumour folate was significantly associated with the overexpression of MCT1, MCT4, LDHA, SLC7A5, SIRT3, and GLUD1." (PMID 36615660, 2022). "The group of NADH-competitive LDHA inhibitors also includes quinoline-3-sulfonamides, which have shown anti-tumor activity in in vitro studies on hepatocellular carcinoma Snu398 cells." (PMID 35628385, 2022).
tumor (continued). "In cancers, LDHA has been identified as an oncogene that can help tumour cells produce large amounts of energy rapidly through glycolysis to support cell growth." (PMID 35090076, 2022). "The expression levels of key glycolytic enzymes, namely GLUT1, ENO1, PGK1, ALDOA, HK1, and LDHA, in the tumor tissues of chemotherapy-resistant and chemotherapy-sensitive groups were examined using IHC analysis." (PMID 34510316, 2022). "Another paper also corroborated these findings through RNA interfering (RNAi)-nanoparticle mediated knockdown of lactate dehydrogenase (LDHA) in tumor cells, which also neutralized tumor pH and increased the infiltration and cytotoxicity of NK and T cells." (PMID 36479131, 2022). "This anti-tumor effect can be augmented when combined with autophagy inhibition by chloroquine, because LDHA inhibition induces protective autophagy." (PMID 36557253, 2022). "In a mouse pancreatic cancer model, a tumor cell cluster upregulated LDHA (a hypoxia-related gene) in the interface area compared with that in the tumor center and had stronger ability for survival and invasion." (PMID 36313703, 2022). "In cancer cells, LDHA converts pyruvate to lactic acid because of elevated tumor aerobic glycolysis, which leads to the pH decreasing in the TME." (PMID 35335881, 2022). "Current knowledge has established that LDHA is involved in tumor initiation, development, progression, invasion, metastasis, angiogenesis, and immune escape." (PMID 36518315, 2022). "LDHA can be activated by upstream kinases via phosphorylation at tyrosine 10 (Y10), thus promoting tumour invasion and metastasis." (PMID 35090076, 2022). "In TME, the inhibition of LDHA also restricts cells with glycolysis as a preferential metabolic mode, such as Tregs, MDSCs and TAMs, which ultimately hinders the progression of tumours." (PMID 36578477, 2022). "To inhibit redox balance, we chose to use phenformin as an in vivo respiratory complex I inhibitor and irradiation to interfere with metabolic adaptations of double LDHA/B KO tumor cells." (PMID 36278433, 2022). "The upregulated SLC2A1 (GLUT1) (T/TA = 9.49), HK2 (T/TA = 36.69), PFKP (T/TA = 15.97), PKM (T/TA = 4.08), and LDHA (T/TA = 8.58) suggested the increased of glucose utilization for lactate fermentation in ccRCC tumor vs. adjacent tissues." (PMID 35440542, 2022). "Representative images demonstrated that upregulation of KCNK3 lead to decreased staining intensity of Ki67, GLUT1, and LDHA in the resected tumor when compared with the control group." (PMID 35963847, 2022). "The LDHA dependency of cancer cells has been demonstrated in several xenograft and genetically engineered mouse models, in which the genetic ablation of LDHA significantly reduces tumor growth." (PMID 35982980, 2022). "In tumor anaerobic glycolysis, LDHA preferentially catalyzing pyruvate to lactate and which is undisputed known as a vital checkpoint." (PMID 35359405, 2022). "The downregulation of LDHA limits the function of Tregs and contributes to a sustainable anti-tumor response during anti-CTLA-4 treatment." (PMID 36620597, 2022). "In tumor cells, LDHA catalyzes the conversion of pyruvate to lactate, then excessive intracellular lactate is excreted from the cytoplasm by monocarboxylate transporters (MCTs) into the TME, thus resulting in an extracellular acidic microenvironment." (PMID 36518315, 2022). "In tumour cells, LDHA plays essential role in initiation, growth, tumour maintenance, progression and metastasis." (PMID 35084545, 2022). "As a consequence, intracellular acidification slows down the glycolytic flux and LDHA activity, thus reducing tumor growth and invasion." (PMID 35348905, 2022). "LDHA inhibitors have been widely explored and proven to suppress tumor growth among different cancers." (PMID 35669414, 2022).
tumor (continued). "The results showed that this molecule inhibited the activity of PDK1 and LDHA, significantly reduced the production of lactate in tumor cells, increased oxygen consumption, and regulated glucose metabolism." (PMID 35957825, 2022). "LDHA is also involved in tumor cells proliferation, angiogenesis, tumor cells invasion and migration." (PMID 35433453, 2022). "The relevance of LDHA for tumor development and growth is underscored by the fact that its inhibition by shRNA or small drug-like molecules can reduce tumor cell growth both in vitro and in vivo." (PMID 35205318, 2022). "Next, we examined the expression of key enzymes catalysing glycolysis such as PFKP, ENO1, PKM and LDHA in ccRCC tumours and the matched controls." (PMID 35672925, 2022). "Silencing of RPN2 also inhibited the expression of HK-2, PDK1, and LDHA in these cells and decreased LDHA level in mouse tumor tissues." (PMID 35156537, 2022). "The expression level of LDHA was high in the whole tumor tissue, and the difference was most significant in the invasion area." (PMID 36685583, 2022). "In particular, it was demonstrated that suppression of LDHA activity inhibited cell growth, suppressed tumor invasion, and induced apoptosis in GC cells." (PMID 35936690, 2022). "GLUT1 increases glucose uptake by tumor cells and produces more lactic acid via glycolysis, whereas LDHA favors the conversion of pyruvate into lactate, the presence of GLUT1 and LDHA can enhance lactic acid production at the source." (PMID 36577992, 2022). "This indicates that LDHA is an enhancer of tumor progression by fueling aerobic glycolysis and LDHB is a suppressor in glycolytic tumor cells." (PMID 36077431, 2022). "Tumor cells can promote lactate production through the enzyme LDHA, thereby destroying tumor-infiltrating T cells as well as IFN-γ in natural killer cells and other cytokines to promote epithelial–mesenchymal transformation, angiogenesis, and invasion." (PMID 36411477, 2022). "LDHA expression in OS tissues was identified to be upregulated compared with para-tumor tissues, and LDHA mRNA expression was significantly up-regulated in patients with metastatic osteosarcoma." (PMID 33664867, 2021). "Suppression of the c-Myc-LDHA axis inhibited tumor growth and progression in PDA cell lines, and the same effects were observed with 2-DG, a glycolysis inhibitor." (PMID 33804240, 2021). "Taken together, these data suggest that LINC00671/LDHA axis regulates PTC tumor growth and lung metastasis in vivo." (PMID 34404767, 2021). "Excess lactate produced by the lactate dehydrogenase-A (LDH-A) in tumor cells is exported from the cytoplasm by the monocarboxylate transporter (MCT), which plays a vital role in facilitating proton-linked lactate transportation across membranes." (PMID 34778068, 2021). "Our results are in line with those previously obtained by Leder’s group, who demonstrated that LDHA knockdown resulted in a compromised ability of tumor cells to proliferate under hypoxia." (PMID 33714987, 2021). "In line with the results from in vitro experiments, LDHA knockdown inhibited tumor growth, reduced lactate level, and enhanced cytotoxic T cell activity." (PMID 34482375, 2021). "We observed that LDHA was mainly localized in the cytoplasm, and that the expression of LDHA was significantly higher in the tumor tissues of COAD patients." (PMID 34307169, 2021). "The Warburg effect mainly occurs in tumor cells, in contrast to normal cells, even in the presence of sufficient oxygen, and during this process, pyruvic acid tends to be catalyzed by LDHA into lactic acid." (PMID 33558466, 2021). "Knockdown of LDHA in tumor cells using RNAi nanoparticles neutralized the pH of the TME, increased infiltration with CD8+ T and NK cells, decreased the number of Tregs, significantly inhibited the growth of tumors and potentiated checkpoint inhibition therapy." (PMID 34079545, 2021).
tumor (continued). "Our study revealed a positive correlation between tumor volume and the degree to which 6‐Gy irradiation induced LDHA upregulation in the GBMJ1 tumor." (PMID 33939204, 2021). "As LDHA executes aerobic glycolysis in tumor cells by catalyzing the conversion of pyruvate to lactate, to determine the metabolic effects of KDM6B silencing in OS cells, we calculated the aerobic glycolysis index in control and KDM6B-KD OS cells." (PMID 33664867, 2021). "Macroscopic xenografts were observed in the pancreatic tissue and liver of nude mice injected with LDHA‐OE Panc‐1 cells after 4 weeks, with significantly higher tumor weight than the wild‐type control (P < 0.05)." (PMID 34185423, 2021). "CLAN-mediated gene silencing efficiently downregulated LDHA expression, decreased lactate secretion, and raised the tumor pH." (PMID 34158861, 2021). "Together, these results suggest that berberine suppressed tumor progression of PAAD in vivo through functional inhibition of LDHA." (PMID 34185423, 2021). "The LDH activity in LS174T WT tumor cells was inhibited with sublethal doses of the pyruvate analog Oxa (60 mM, 48 h) and the novel LDHA/B/C inhibitor GNE (10 μM, 24 h)." (PMID 34359663, 2021). "In our study, we found that KDM6B regulates glycolysis in tumor cells via modulating lactate dehydrogenase A expression, and then affect the progress of OS." (PMID 33664867, 2021). "Lactate production by tumour cells mediated by lactate dehydrogenase A can limit IFN-γ production in tumour infiltrating T cells and NK cell activation." (PMID 33860061, 2021). "Consistently, LDHA shRNA increases the cytotoxic potential of T cells toward cancer cells in a T-cell–mediated tumor cell killing assay." (PMID 34482375, 2021). "It has been traditionally accepted that an increase of the enzyme lactate dehydrogenase-A (LDH-A) accompanies tumor formation and is the driver of increased pyruvate-to-lactate conversion observed in hyperpolarized MR studies." (PMID 34685601, 2021). "While increases in LDHA following radiation have been observed in vitro, our work presents the first observation of upregulation of LDHA in response to radiation exposure in a GSC‐derived tumor using an orthotopic model." (PMID 33939204, 2021). "A positive correlation between lactate dehydrogenase A (LDH-A), high local lactate levels, and tumor progression has been documented in various tumors." (PMID 33868292, 2021). "These include many of the genes involved in tumorigenesis: VEGF, platelet-derived growth factor (PDGF), aldolase A, enolase 1, and LDHA, which regulate tumor angiogenesis and the process of abnormal glycolysis." (PMID 34604067, 2021). "In GBM, HK2 has been shown to be a key mediator of aerobic glycolysis and tumor growth, which is in line with our observed expression ratio of LDHA/LDHB in the IDH wild-type enriched patient cluster." (PMID 33532725, 2021). "Consistent with the in vitro data, inhibition of lncRNA MDFIC-7 expression suppressed the mRNA expression of GLUT1, HK2, PDK1 and LDHA in the xenograft tumor tissues." (PMID 34621682, 2021). "Significant increases of CD69, IFNɣ, CD107a, CD314, and NKp46 in tumor infiltrated NK cells in LDHA knockout xenograft tumor." (PMID 34482375, 2021). "In both melanoma and pancreatic adenocarcinoma cell lines, knockdown of LDHA resulted in increased NK cell proliferation, IFNγ and granzyme B production, and tumor control by immune cells." (PMID 33670082, 2021). "Studies have found LDHA targeting tumor cells and LDHB targeting stromal cells influence tumor proliferation." (PMID 33718202, 2021). "STAT3/LINC00671/LDHA axis regulates glycolysis, tumor growth, and lung metastasis of PTC both in vitro and in vivo." (PMID 34404767, 2021). "Lactate dehydrogenase A (LDH-A) is one of the critical enzymes in the glucose metabolism pathway, and IL-4 can upregulate the expression of the glucose metabolism-related gene LDHA, thereby promoting the proliferation of tumor cells." (PMID 34976805, 2021).